GIPC3 (GIPC PDZ domain containing family member 3)
Description:
Required for postnatal maturation of the hair bundle and long-term survival of hair cells and spiral ganglion.
Synonyms: C19orf64; DFNB95; DFNB15; DFNB72
Tractability: PROTAC: ubiquitination databases record sites on it.
Gene: Protein-coding gene on chromosome 19 (3,585,478 to 3,593,541, forward strand). Ensembl gene ENSG00000179855.
Subcellular location (Human Protein Atlas): Nucleoplasm; Golgi apparatus; Nuclear bodies
Gene Ontology:
Molecular function: protein binding
Genetic constraint (gnomAD): Loss-of-function variants: 16 observed, 25.25 expected, observed/expected ratio (o/e) 0.63, 90% interval 0.43 to 0.96. The upper end of that interval is the gene's LOEUF score, 0.96, which puts it in group 4 of 6, group 1 being the genes least tolerant of losing a copy. Missense variants: 440 observed, 417.63 expected, observed/expected ratio (o/e) 1.05, 90% interval 0.97 to 1.14. Synonymous variants: 194 observed, 173.77 expected, observed/expected ratio (o/e) 1.12, 90% interval 0.99 to 1.26.
Gene-disease validity (ClinGen):
ClinGen rates the evidence that GIPC3 causes each of these diseases.
nonsyndromic genetic hearing loss (autosomal recessive): Definitive. A disease characterized by hearing loss that is not part of a larger syndrome.
Homologues: Orthologues: chimpanzee GIPC3 (99% identical), dog GIPC3 (96% identical), pig GIPC3 (93% identical), guinea pig GIPC3 (89% identical), mouse Gipc3 (86% identical), rat Gipc3 (81% identical), tropical clawed frog gipc3 (75% identical), macaque GIPC3 (70% identical), zebrafish gipc3 (70% identical), Drosophila melanogaster kermit (51% identical), Caenorhabditis elegans gipc-2 (34% identical), Caenorhabditis elegans gipc-1 (32% identical). Paralogues in human: GIPC1 (64% identical), GIPC2 (55% identical).
Diseases named in the same sentence as GIPC3 in open-access papers:
GIPC3 is named in the same sentence as 8 diseases in open-access papers, as found by Europe PMC text mining. Sharing a sentence is not in itself a finding about the gene and the disease. The quoted sentences say what the papers report.
deafness (11 papers, 2012 to 2023). An inherited or acquired condition characterized by the complete loss of the ability to hear from one or both ears. "Defects of the human GIPC3 gene cause deafness and Gipc3 disruption in mice led to audiogenic seizures and progressive hearing loss." (PMID 37800695, 2023). "Defects of the human GIPC3 gene cause human deafness and Gipc3 disruption in mice leads to audiogenic seizures and progressive hearing loss." (PMID 35966010, 2022). "Screening for variants of GIPC3 is essential for early detection of hearing loss in children and eventually treatment of deafness." (PMID 36704659, 2022). "GIPC3 was the causal gene of autosomal recessive deafness (type 15), non-syndromic genetic deafness and audiogenic seizures." (PMID 32682410, 2020). "Using a minimum depth of coverage of 8× as an initial filter, they missed a novel variant in GIPC3, a gene which is known to be involved in deafness." (PMID 23155419, 2012). "It is unclear how GIPC3 mutations cause sensorineural deafness and acoustic seizures." (PMID 36704659, 2022). "GIPC3 is one of over a hundred different genes with variants causing human deafness." (PMID 36704659, 2022). "Targeted NGS of 127 hearing loss‐related genes was carried out in the 9 probands, which allowed us to detect 5 reported and 5 novel variants in 6 distinct deafness genes including CDH23, GIPC3, MYO7A, TRIOBP, TECTA, and OTOF." (PMID 32864763, 2020). "Autosomal recessive deafness 15 (DFNB15), also known as DFNB72 or DFNB95, is caused by homozygous mutations in the GIPC3 (GAIP interacting protein 3, C terminus) gene on chromosome 19p13.3." (PMID 25140308, 2014). "This might, for instance, involve the adapter and PDZ‐domain protein Gipc3, defective in human deafness, required for the modiolar–pillar gradient of maximal synaptic Ca2+ influx." (PMID 33346936, 2021). "Twelve homozygous mutations in known deafness genes, of which eight are novel, were identified in 12 families: MYO15A-p.Q1425X, -p.S1481P, -p.A1551D; LOXHD1-p.R1494X, -p.E955X; GIPC3-p.H170N; ILDR1-p.Q274X; MYO7A-p.G2163S; TECTA-p.Y1737C; TMC1-p.S530X; TMPRSS3-p.F13Lfs*10; TRIOBP-p.R785Sfs*50." (PMID 23226338, 2012). "If GIPC3 was not known as a cause of deafness we could have concluded that the variant in ZNF57 was causative." (PMID 22363784, 2012).
hearing loss (9 papers, 2012 to 2025). "Aberrant expression of GIPC3 has been evidenced to correlate to the audiogenic seizures and sensorineural hearing loss in mouse and human." (PMID 36301034, 2022). "In patients with sensorineural hearing loss, there are biallelic nonsense, missense, and frameshifting mutations of the GIPC3 gene." (PMID 34071867, 2021). "After finding potential regions through autozygosity mapping we identified two novel rare variants to cause hearing loss in this study (GIPC3 p.H170N and ZNF57 p.T443M)." (PMID 22363784, 2012). "Variants of human GIPC3 are associated with non-syndromic hearing loss." (PMID 36704659, 2022). "In Saudi Arabia, several gene mutations (e.g., GIPC3, ILDR1, W77R, MYO15A, TMC1, TMPRSS3, and DFNB67) have been identified in families and are associated with childhood hearing loss." (PMID 40918669, 2025). "In humans, GIPC3 mutations can lead to NSHL, a disorder in which hearing loss is caused by damage to the inner ear, the auditory nerve, or the auditory center of the brain." (PMID 36704659, 2022). "We can speculate that this mutation also may contribute to hearing loss or more likely it might contribute to the susceptibility for another phenotype which was not considered here and that these two variants (ZNF57 p.T443M and GIPC3 p.H170N) are found to co-segregate." (PMID 22363784, 2012).
sensorineural hearing loss (6 papers, 2012 to 2022). "The homozygous variant NM_133261.3(GIPC3):c.245A>G (p.Asn82Ser) is the major molecular cause of hereditary sensorineural hearing loss in 23% of Chuvash patients (OMIM #601869)." (PMID 34071867, 2021). "Moreover, in Chuvash population, genetic variant of GIPC3 was indicated to associate with hereditary nonsyndromic sensorineural hearing loss." (PMID 36301034, 2022). "Moreover, Gipc3 mutations induce non-syndromic sensorineural hearing loss in humans, and Gipc3 disruption enhances Ca2+ influx and exocytosis in IHCs, reverses the spatial gradient of maximal Ca2+ influx in IHCs, and increases the maximal firing rate of SGNs at sound onset." (PMID 35966010, 2022). "Six missense mutations and one shift mutation in GIPC3, located at DFNB72 on chromosome 19p, were found in seven Pakistani families with varying degrees of sensorineural deafness." (PMID 36704659, 2022). "While this work was ongoing a missense mutation in Gipc3 was reported to be associated with age-related sensorineural hearing loss in the mouse, and two missense variants in GIPC3 (MIM 608792) in two small families with sensorineural hearing loss." (PMID 22363784, 2012).
anorexia nervosa (1 paper, 2020). A disorder most often seen in adolescent females characterized by a refusal to maintain a minimally normal body weight, an intense fear of gaining weight, a disturbance in body image, and, in postmenarcheal females, the development of amenorrhea. "Across the four anorexia nervosa associated gene sets, four genes overlap between the Lutter damaging variants and Negraes iPSC derived gene set (TNFRSF10A, SCGB1A1, IFIT3, and GIPC3; hypergeometric test, p < 0.02)." (PMID 32651428, 2020).
nonsyndromic sensorineural hearing loss (1 paper, 2012). "Biallelic GIPC3 mutations have recently been reported to cause autosomal recessive nonsyndromic sensorineural hearing loss." (PMID 22363784, 2012).
systemic lupus erythematosus (1 paper, 2022). An autoimmune multi-organ disease typically associated with vasculopathy and autoantibody production. "In this study, we found that miR‐762 was significantly upregulated in Systemic lupus erythematosus (SLE) and neuropsychiatric SLE (NPSLE), and overexpression of miR‐762 significantly suppressed GIPC3 expression." (PMID 36301034, 2022).
GIPC3 also shares sentences with these, for which no sentence is quoted: autosomal recessive deafness (2 papers); Perrault syndrome (1).